IL6 (interleukin 6)
Diseases named in the same sentence as IL6 in open-access papers (continued):
Sharing a sentence is not in itself a finding about the gene and the disease.
ulcer (continued). "A direct comparison between the ulcer + OMP and ulcer + OMP-NS groups revealed that the OMP-NS formulation significantly decreased levels of HMGB1, NLRP3, NF-κB, TLR-2, MyD88, IL-1β, IL-6, and TNF-α." (PMID 40563542, 2025). "To evaluate the anti-inflammatory effect of the CHRs on ulcers, we measured the levels of pro-inflammatory cytokines, including TNF-α, IL-6, IL-18, and IL-12 in the serum." (PMID 40283949, 2025). "The ulcer control rats showed the highest inflammation rate represented by higher TNF‐α, IL‐6 cytokines, and lower IL‐10 levels compared to all groups." (PMID 40034223, 2025). "TNF-α and IL-6 are key mediators of gastric inflammation, with TNF-α initiating acute inflammatory responses and delaying ulcer healing by inhibiting angiogenesis and cell proliferation." (PMID 39859072, 2025). "In the present study, a progressive increase in the levels of IL-6, TNF-α, and CRP was observed across the control, pre-ulcer, and ulcer groups, indicating that inflammation plays a critical role in the early pathogenesis of DFUs." (PMID 40364880, 2025). "A chemically induced ROU model in rats (n = 8 per group) was established to evaluate the effects of AF-SD on ulcer area, serum inflammatory cytokines (TNF-α, IL-6), vascular endothelial growth factor (VEGF) levels, and histopathological outcomes." (PMID 41599609, 2025). "Together, these results demonstrate that AF-SD effectively suppressed ulcer-induced upregulation of the pro-inflammatory cytokines TNF-α and IL-6, exhibiting a superior anti-inflammatory effect compared with the clinically used spray." (PMID 41599609, 2025). "In a rat DFU model, H‐ADSCs‐Exo administration reduced ulcer size, increased angiogenesis (VEGF/CD31 expression), and decreased inflammatory markers (TNF‐α, IL‐6)." (PMID 40584821, 2025). "Therefore, reducing levels of TNF-α, IL-1β, and IL-6 may promote ulcer healing." (PMID 38398633, 2024). "Ulcer model group had significantly higher blood levels of TNF‐α and IL‐6 (98.5%, p < 0.05 and 111.6%, p < 0.05, respectively) than control group." (PMID 39723096, 2024). "Ulcer group showed significant increases in MDA (64%) and TNF‐α and IL‐6 levels (98.5% and 111.6%), and decreases in ferric reducing antioxidant power and 2,2‐diphenyl‐1 picrylhydrazyl (FRAP, DPPH, and thiol levels [26%, 14.39%, and 26%]) compared to controls." (PMID 39723096, 2024). "MD-4 significantly (p < 0.05) increased the superoxide dismutase (SOD) levels in ulcers and reduced pepsin, TNF-α, and IL-6 levels." (PMID 36292625, 2022). "We analyzed the ulcer area, conducted histological analysis, and measured the levels of the inflammatory cytokines TNF-α, IL-6, IL-1β, and IFN-γ, and anti-inflammatory cytokine IL-10 by ELISA." (PMID 35456589, 2022). "More so than in the pre-treated animals, the EGb 761-treated groups showed improved score, levels, and expressions of the ulcer index, MDA, GSH, NO, IL-6, TNF-α, IL-1β, COX-2, and PCNA." (PMID 36080365, 2022). "In this study, pre-treatment with ZJP (1, 2, and 4 g/kg) led to a dose-dependent decrease in the contents of TNF-α, IL-6 and MPO compared with the ulcer model group." (PMID 35938492, 2022). "When compared to the ulcer group, prophylactic treatment with EGb 761 attenuated the elevation of the gastric tissue cytokines; TNF-α (178.3 ± 9.72 pg/mL, p < 0.001) and IL-6 (230 ± 13.73 ng/L, p < 0.001)." (PMID 36080365, 2022). "In comparison with the control group, IND-treated rats showed visible multiple ulcers with ulcer index, serum MDA, IL-2 and IL-6 were elevated while IL-10, PGE2, NO, and eNOS mRNA expression were significantly reduced." (PMID 33833690, 2021). "The expression of IL-6 and TNF-α in serum in the three induced stress ulcer groups was increased compared with the normal group, indicating that overexpression of inflammatory factors occurs during gastric mucosal injury." (PMID 33628315, 2021).
ulcer (continued). "In contrast with control cohort, the amounts of IL-1β, IL-6, TNF-α, IL-18 in ulcer model cohort increased to 8.52-, 5.24-, 7.86-, and 4.16-folds, respectively." (PMID 34975497, 2021). "In the current study, we evaluated the levels of IL-1, IL-6, IL-8, and TNF-α of the secretions of ulcer surface at different time points during the treatment." (PMID 29234410, 2017). "TNF-α, IL-6 and MIP-1 expression in magnet-implanted ulcers was elevated on the day after forming the ulcer (day 0) as a control (P < 0.01)." (PMID 28687753, 2017). "The expressions of IL-1, IL-6, IL-8, and TNF-α in the ulcer surface secretions of all samples were increased at the early stage of ulcer formation." (PMID 29234410, 2017). "Inflammatory cytokine TNF-α, IL-6 and MIP-1 levels were lower in ulcers treated with mixed cell sheets than in untreated ulcers." (PMID 28687753, 2017). "Sesamol significantly decreased gastric ulceration and hemorrhage and inhibited mucosal TNF-α, IL-1β, and IL-6 production and NF-κB activity in WIR-treated rats." (PMID 23984371, 2013). "In ethanol-induced gastric ulcer rats, DDP exerted dose-dependent protection: low doses (100 mg/kg/d) reduced ulcer index, increased SOD/GSH-Px (1.5–1.8-fold), decreased MDA (30–35%), and elevated PGE2; high doses (400 mg/kg/d) further inhibited serum TNF-α/IL-6 (25–40%) and improved histopathology." (PMID 41008230, 2025). "Considering the broad role of inflammatory cytokines in the regulation of the WH process, we evaluated the expression of COX2 and pro-inflammatory cytokines, namely IL1β, IL6, TGFβ, and TNFα, that are important for cell proliferation and the synthesis of the ECM, both in normal-HDFs and ulcer-HDFs." (PMID 38671778, 2024). "TNF‐α and IL‐6 levels dropped in the treated groups as compared to the ulcer group; these changes were significant for TNF‐α in the Jangale (56.9%) and eucalyptus (52.39%) groups, and for IL‐6 in the Chand Giah (30.37), Annaab (70.22), and eucalyptus (79.2%) groups." (PMID 39723096, 2024). "In this study, we proposed that the ability of Cls to block ROS, IL-1β, IL-6, TNF-α, NF-κB, and caspase-3 as well as increase pErk-1, NO, PECAM-1, and PPAR-γ levels partly explains why it protects the stomach against ethanol-induced ulcer." (PMID 38884677, 2024). "Thus, in this study, we evaluated the effect of the exposure to a PRF-EMF on ulcer-HDFs, observing a significant increase in the expression levels of IL1β, IL6, COX2, and TGFβ with respect to unexposed normal-HDFs and ulcer-HDFs." (PMID 38671778, 2024). "The biomarkers selected for the panel include tumor necrosis factor–α (TNF-α), interleukin-6 (IL-6), and IL-8, which are elevated in wound fluids obtained from nonhealing ulcers as compared to healing ulcers." (PMID 34020961, 2021). "The extract significantly reduced the elevated levels of IKκB, NF-κB, TNF-α, IL-6, iNOS, and lipid peroxidation; increased the reduced level of glutathione peroxidase (GPx) activity; and reduced glutathione (GSH) in the indomethacin-induced ulcer model." (PMID 33530540, 2021). "In our study, the majority of serum samples had no detectable IL-6; however, it was detected in most saliva samples, showing the highest levels in the BD group with active ulcers." (PMID 35003055, 2021). "Further analysis revealed that IL-6 levels were also significantly higher in the saliva of BD patients with ulcers (BD-MA) than those without (BD-MQ, p=0.03)." (PMID 35003055, 2021). "For example in MRSA-infected mice ulcers, treatment with Epinecidin-1 decreased serum levels of the proinflammatory cytokines TNF-α, IL-6, and MCP-1, and regulated the recruitment of monocytes and clearance of lymphocytes around the wounded region during healing." (PMID 31138331, 2019). "We did not observe a statistical interaction between IL-6 levels and the presence of ulcers in the present study, and IL-6 predicted outcomes equally well in patients without ulcers." (PMID 31341203, 2019).
ulcer (continued). "Moreover, KFX (5,10 mL/kg) increased the prostaglandin E2 (52%) and cyclooxygenase-1 (30%) levels, and improved malondialdehyde (54%), superoxide dismutase (58%), catalase (39%), and nitric oxide (11%) and TNF-α (9%), IL-6 (11%), MMP-9 (54%) and MMP-2 (53%) of ulcer tissue." (PMID 31696757, 2019). "Stability of human recombinant cytokines IL-6 and CXCL8, and histatin variants (Hst1, Hst2, cyclic Hst1, minimal active domain of Hst1) in the presence of chronic wound extracts isolated from non-healing ulcers, was monitored by capillary zone electrophoresis." (PMID 27018788, 2016). "In addition, γKetoC-treated mice showed decreased epithelial cell disruption (focal erosion and ulcers) and inflammatory cell infiltration in the colon tissue and increased number of crypts, and γKetoC administration tended to decrease concentrations of TNF-α, IL-6, and IL-12p40 in serum." (PMID 38745644, 2024). "In parallel, excessive inflammation mediated by IL-6 and TNF-α remains a well-known barrier to DFU closure; elevated levels of these cytokines in non-healing ulcers lead to continual macrophage M1 polarization and inhibited keratinocyte migration." (PMID 40728954, 2025). "IL-6 and TNF-α proinflammatory factors are amplified in chronic non-healing ulcers, postponing the healing process." (PMID 31137844, 2019). "Elevated levels of cytokines such as tumor necrosis factor α (TNF-α), interleukin-6 (IL-6), interleukin-8 (IL-8) and transforming growth factor-β1 (TGF-β1) have been found in patients suffering from non-healing leg ulcers as compared to healing ulcers." (PMID 35049629, 2021).
fungal infection (101 papers, 2008 to 2026). "Concurrent use of interleukin-6 inhibitors like tocilizumab also acts as a risk factor for developing fungal infections, particularly CAPA." (PMID 41156674, 2025). "They produce cytokines such as TNF and IL-6, both of which play a role in determining susceptibility to fungal infections." (PMID 23675302, 2013). "Whether IL-6 plays a role in modulating innate immunity and adaptability during fungal infection, thus contributing to the body’s susceptibility to IFI, necessitates further research for confirmation." (PMID 39040601, 2024). "Furthermore, it is doubtful that one or two doses of an IL-6 antagonist would cause consequences like fungal infections or jaw osteonecrosis, which are common in people using these medications on a monthly basis for chronic illnesses like RA." (PMID 36506506, 2022). "On the other hand, IL-6 is frequently detectable in CSF during viral, bacterial, and fungal infections, as well as CNS inflammatory diseases—especially bacterial meningitis." (PMID 40881684, 2025). "Many of these cytokines, such as IFNγ, TNFα, GM-CSF, IL-6, IL-17a, and GRO-α, are associated with protection against fungal infections." (PMID 38469300, 2024). "As regarded fungal infection, the genotypes (GG, GA, and AA) frequency of IL-17A and The genotypes (CC, CG, and GG) frequency of IL-6 G-174C showed significant differences between patient groups and control group p = 0.002,0.01respectively." (PMID 39289412, 2024). "The GLM suggested that patients with an IL-6 concentration < 10pg/ml are more vulnerable to developing a bacterial/fungal infection." (PMID 38616284, 2024). "It is known that TNF-α and IL-6, as critical inflammatory mediators, can resist fungal infection and promote the infiltration of inflammatory cells to remove pathogens, such as increasing the killing of phagocytosed S. schenckii." (PMID 37141335, 2023). "In the presence of IL-1β and TGF-β, IL-6 leads to polarization towards the Th17 subset, which is involved in immune defense against extracellular bacterial and fungal infections." (PMID 37018291, 2023). "IL-6 and IL-8 are expressed in keratinocytes and fibroblasts in response to fungal infection and secreted in sufficient amounts to be detectable by enzyme-linked immunosorbent assay (ELISA) in the CCM of skin models." (PMID 35499318, 2022). "Lastly, we measured the impact of flagellin pre-exposure on the inflammatory response of BEC after 15 h of fungal infection by quantifying IL-8 and IL-6 in cell supernatants." (PMID 36547601, 2022). "The results further revealed significant differences in TNF-β, IL-12p70, IL-6, IL-8, and IL-10 between the pulmonary bacterial infection group and the fungal infection group (P < 0.05)." (PMID 36319826, 2022). "Further, a significant variation in IL-17A, TNF-β, IL-1β, IL-2, IL-4, IL-6, IL-8, IL-10, IL-22, and IL-12p70, between the uninfected group and the pulmonary bacterial and fungal infection group (P < 0.05) was observed." (PMID 36319826, 2022). "Patients with RVVC showed higher levels of IL-1β and IL-6 in CVL than Control individuals and higher IL-6 levels than patients with the acute form of the mycosis." (PMID 35049960, 2021). "IL-6-deficient mice are more susceptible to invasive candidiasis than wild type mice, which suggests that IL-6 release is fundamental during fungal infection." (PMID 34684298, 2021). "However, long-term inhibition of IL-6– or IL-17A–induced proinflammatory effects by Ab drugs may hamper the immunity of RA patients and increase the risk of adverse events such as serious tuberculosis infection or fungal infection." (PMID 31194726, 2019). "During the middle-advanced stage of fungal infection, the IL-1β, IL-6, IL-8, and IFN-γ levels in the aqueous humor were significantly increased compared to non-keratitis controls." (PMID 29673332, 2018).
fungal infection (continued). "Here, the authors show that expression of MST1 by dendritic cells limits IL-6 production and thereby controls Th17 differentiation in immunity to fungal infection and experimental autoimmune encephalomyelitis." (PMID 28145433, 2017). "Another important pathway in the immune response against fungal infections is Th17, which is associated with increased IFN-γ production by T cells and influenced by IL-6 kinetics." (PMID 29371546, 2017). "Studies have shown that it modulates interleukin 6 (IL6) release in human dendritic cells (DCs) following fungal infection." (PMID 28797245, 2017). "Since pro-inflammatory cytokines are the main cytokines produced upon fungal infection, we measured production of IL-6 and TNF-α." (PMID 26431038, 2015). "Utilizing in vitro neutrophil killing assays and a model of fungal infection of the cornea, we demonstrated that Dectin-1 dependent IL-6 production regulates expression of iron chelators, heme and siderophore binding proteins and hepcidin in infected mice." (PMID 23853581, 2013). "Taken together, results from this set of studies indicate that following fungal infection of the cornea, Dectin-1 dependent IL-6 production induces local and systemic host responses that limit microbial access to iron." (PMID 23853581, 2013). "Protective immunity against fungal infections via TH-17 cellular responses requires the expression of IL-1β, IL-23 and IL-6 by DCs." (PMID 21283787, 2011). "During fungal infection in mice, Dectin-1-mediated production of IL-23 and IL-6 promotes the development of Th17 responses." (PMID 19291703, 2009). "We observed minimal astrogliosis in IL-6−/− brain tissue infected with Cn; however, this was not surprising because these mice have previously shown impaired astroglia activation, indicating the importance of IL-6 in stimulating glia responses to fight this CNS mycosis." (PMID 39334365, 2024). "Through a complex biological process involving oral epithelium lesions, oral bacterial super infections and pro-inflammatory cytokines alteration such as TNF-α, iterleukin-1 (IL-1), interleukin-6 (IL-6), OM can manifest as severe ulceration and fungal infection of the mouth (e.g., oral candidiasis)." (PMID 36978952, 2023). "Immunomodulation by blocking the IL-6 pathway in fungal infections could prove a double-edged sword, providing a state of immune tolerance at the expense of fungal persistence in the host." (PMID 37367619, 2023). "Conversely, when co-induced with TGF-β and IL-6, CD4+ T cells differentiate into CD4+Th17 cells, a cell type known for secreting IL-6 and IL-17 while playing a significant role in defending against extracellular bacterial and fungal infections, inflammatory responses, and autoimmune reactions." (PMID 37941053, 2023). "Again, fungal infections showed equal or even lower IL-6 levels." (PMID 36675638, 2023). "The author hypothesized that the coronavirus vaccine increased serum levels of IL-6, which, in turn, increased serum ferritin levels, thereby creating an environment that is conducive to the development of fungal infections." (PMID 36718337, 2022). "Overall the cytokine pattern observed in this study using long-term dexamethasone treatment and concomitant fungal infection, namely lowering of IL-1β, IL-6, and IL–8 and an increase in IL-10, implicates a shift from Th1 towards Th2, a pattern associated with suppressing antifungal properties." (PMID 33803702, 2021). "IL-6 and IL-8 will also increase in patients with fungal infections such as Candida." (PMID 34925324, 2021). "Severe COVID-19 disease is associated with an increase in pro-inflammatory markers, such as IL-1, IL-6, and tumor necrosis alpha, less CD4 interferon-gamma expression, and fewer CD4 and CD8 cells, which increase the susceptibility to bacterial and fungal infections." (PMID 34036149, 2021). "Interestingly, a fungal infection of Il1a-/- BMDMs resulted in reduced IL-6 production, whereas exogenous rIL-1α rescued IL-6 levels." (PMID 31425553, 2019).